EGFR (epidermal growth factor receptor)
Diseases named in the same sentence as EGFR in open-access papers (continued):
Sharing a sentence is not in itself a finding about the gene and the disease.
depression (36 papers, 2012 to 2026). "Several observational studies have shown that EGFR-mutant NSCLC is associated with lower depression rates and severity." (PMID 34877613, 2022). "Patients with an actionable mutation such as EGFR have lower inflammation and lower rates of depression." (PMID 34056574, 2020). "In a clinical investigation on NSCLC patients to examine the relationship between the severity of the major depressive disorder and EGFR mutation, the results indicated lower depression severity in EGFR-mutated NSCLC patients than with patients harboring wild-EGFR." (PMID 38505421, 2024). "It is a new question, whether the relationship between EGFR mutational status and depression is mediated by other mechanisms, besides inflammation, that protect patients from psychological impairment." (PMID 34877613, 2022). "STRING analysis further underscored the shared roles of proteins IL15, C–C Motif Chemokine Ligand (CCL)−2 and CCL20 in the context of air pollution-induced depression and anxiety, potentially highlighting EGFR's critical role in depression." (PMID 40611827, 2025). "Topological analysis of the bioactive-target-pathway network indicated that MAPK1, PIK3R1, EGFR, AKT1, and SRC were the core targets enriched in crucial signaling pathways associated with treating depression by A. laxiflora." (PMID 38505421, 2024). "Multiple pharmacological network studies have suggested the role of EGFR in major depressive disorder." (PMID 38505421, 2024). "In a recent publication, less depression in EGFR mutant NSCLC patients was documented, probably mediated by lower CRP‐related inflammation." (PMID 34877613, 2022). "Among them, EGFR is highly expressed in a variety of malignancies, and depression is common in oncology patients (four times more prevalent than in the general population)." (PMID 34471414, 2021). "This matches with the hub genes from PPI network, in which EGFR has been proved to be a significant depression-related gene, MAOA and MAOB are crucial target genes of various mental diseases, and MAOA is particularly important in depression and anxiety." (PMID 32182911, 2020). "The epidermal growth factor receptor (EGFR) influences the synaptic transmission efficiency of serotonin (5-HT) and dopamine (DA) neurons, and its overexpression may exacerbate depression through inflammatory mechanisms." (PMID 40520679, 2025). "EGFR (epidermal growth factor receptor) has been found to be correlated with the occurrence of depression in individuals diagnosed with severe MDD, and a significant increase in EGFR expression was observed in mice treated with propofol, which can be effectively inhibited by irisin." (PMID 38985081, 2024). "Hence, ERK1/2-MAP kinase and Akt cascade signaling by CRF1R regulated by Src, PYK2, and EGFR may have critical roles in stress-induced anxiety and depression." (PMID 31920979, 2019). "The abnormal expression of ERBB (epidermal growth factor receptor, EGFR, epidermal growth factor receptor) signaling pathway can lead to oligodendrocytes (OL) abnormalities, which results in dopaminergic dysfunction, and it may be associated with depression." (PMID 22348066, 2012). "Molecular docking analysis results exhibited that core targets of depression, such as SRC, EGFR, PIK3R1, AKT1, and MAPK1, bind stably with the analyzed bioactive compounds of A. laxiflora." (PMID 38505421, 2024). "Among the top 10 hub gene targets, MAPK1, AKT1, PIK3R1, EGFR, STAT3, and SRC were the most enriched targets in the selected KEGG pathway, suggesting their critical role in the pathogenesis of depression." (PMID 38505421, 2024). "Basic studies demonstrated that modified BXXXD, a formula similar to GJHQHLRSD, can effectively alleviate UC as well as relieve depression and UC through targeting VEGFA, TNF, STAT3, EGFR, and others." (PMID 34539797, 2021).
depression (continued). "PPI network analysis showed that VEGFA, EGFR, CASP3, IL6, ESR1, and other targets have important implications in the treatment of depression with XPJYD." (PMID 34257681, 2021). "The results from the IPA database analysis predicted that ERK1/2, akt, Mapk, EGFR and NTS,which have been reported as highly correlated with the pathogenesis of depression, are hub genes that discriminate the effects of DG and VLX on the PFC in mice." (PMID 28852120, 2017). "Specifically, we observed that CUMS-induced depression models exhibited profound molecular dysregulation characterized by significant BDNF suppression, pathological EGFR overexpression, ERK2 downregulation, pro-inflammatory JUN elevation, RAF1 repression, and chronic stress-driven TNF upregulation." (PMID 41438694, 2026). "Equally significant is the pathological EGFR overexpression in depression models, which has not been previously emphasized in depression research." (PMID 41438694, 2026). "Furthermore, STRING analysis underscored the shared roles of specific proteins, including EGFR, IL15, CCL2, and CCL20, in the context of air pollution-induced depression and anxiety, highlighting the involvement of immune-related processes and pathways." (PMID 40611827, 2025). "The data suggested that MAPK1, EGFR, and AKT1 were the major protein targets for achieving the desired pharmacological effect, whereas, quercetin and 3-acetylursolic acid might be predicted as the most active phytoligands of A. laxiflora to treat mental depression." (PMID 38505421, 2024).
medulloblastoma (36 papers, 2009 to 2026). A malignant, invasive embryonal neoplasm arising from the cerebellum. "Studies have shown that inactivation of the EGFR/STAT3 signal axis causes cell apoptosis of medulloblastoma." (PMID 39338323, 2024). "In medulloblastoma, increased copy number of the platelet-derived growth factor receptor alpha (PDGFRα) and overexpression of the epidermal growth factor receptor (EGFR) are associated with poor outcome." (PMID 25596739, 2015). "Aberrant activation of the EGFR signaling cascade has been associated with poor prognosis in medulloblastoma." (PMID 25052069, 2014). "Previously, we reported on the trans-activation of the EGFR by PDGF-BB in childhood medulloblastoma cells." (PMID 29298329, 2018). "ID3 knockdown decreased the proliferation and increased apoptosis of medulloblastoma cells and ID3 was associated with the EGFR-Akt pathway." (PMID 28283800, 2017). "MET and EGFR were highly activated in primary medulloblastoma samples and subsequently high percentages of medulloblastoma cells expressed these RTK’s." (PMID 26496080, 2015). "This motivates to computationally model the interactions between SHH and EGFR dependent pathways in Daoy cells as a presumable model system for medulloblastoma." (PMID 26571415, 2015). "This motivates to investigate the interplay between the SHH and EGFR dependent pathways in a presumable medulloblastoma model system from a computational point of view." (PMID 26571415, 2015). "Expression of EGFR and ErbB2 is in agreement with previous studies in medulloblastoma cell lines and primary tissue expression, in which expression of EGFR and ErbB2 was detected in varying percentages." (PMID 26496080, 2015). "Previously with kinome profiling, we observed MET and EGFR/ErbB2 peptide activity in primary medulloblastoma samples." (PMID 26496080, 2015). "Together, these data suggest that activation of EGFR in the presence of ouabain induces a cellular stress response in medulloblastoma cells." (PMID 25052069, 2014). "Our results confirm that uPAR and MMP-9 regulate EGFR/STAT3 regulated signalling pathway in medulloblastoma." (PMID 22984561, 2012). "Our results showed that silencing uPAR and MMP-9 in the medulloblastoma cells significantly inhibited the activation (phosphorylation) of EGFR." (PMID 22984561, 2012). "Even in the present study, we determined that the knockdown of uPAR and MMP-9 reduced the expression of total EGFR in medulloblastoma." (PMID 22984561, 2012). "In an independent experiment we attempted to confirm that uPAR and MMP-9 induces the transactivation of EGFR in medulloblastoma cells lines." (PMID 22984561, 2012). "Subsequently our antibody blocking experiment confirmed that blocking EGFR inhibited the activation of uPAR/MMP-9 induced STAT3 in medulloblastoma cell lines." (PMID 22984561, 2012). "Invasiveness in medulloblastoma is mediated by several receptor activation pathways, such as platelet derived growth factor receptor and epidermal growth factor receptor." (PMID 19594892, 2009). "ERK1/2 activation in medulloblastomas can occur following activation of growth factor receptors, such as EGFR, PDGFR, IGF1R and CXCR4." (PMID 19594892, 2009). "We speculate that the activation of the downstream targets of PDGFRβ in the AD cells is due to cross-talk between this receptor and the neighboring EGFR, a finding we previously reported to occur in childhood medulloblastoma cells." (PMID 29298329, 2018). "Furthermore, we show that EGFR and ErbB2 are highly and ErbB3 and ErbB4 are hardly expressed on the cell surface of our medulloblastoma cell lines." (PMID 26496080, 2015). "Flow cytometry analysis revealed that MET (mean±sd: 74.9% ± 13.9%), EGFR (mean±sd: 77.4% ± 10.9%) and ErbB2 (mean±sd: 67.8% ± 10.3%) are highly expressed in all medulloblastoma cell lines, whereas ErbB3 (mean±sd: 4.0% ± 3.6%) and ErbB4 (mean±sd: 1.5% ± 2.1%) are barely expressed at all." (PMID 26496080, 2015).
medulloblastoma (continued). "While cardiac glycosides might not prove useful in all tumor types as anticancer therapeutics, we suggest that Na,K-ATPase is an attractive target to develop novel therapeutic strategies for medulloblastoma with aberrant activation of EGFR signaling." (PMID 25052069, 2014). "Taken together, these data show that EGFR/HER2 signaling can be activated by EGF in DAOY cells and thus, DAOY cells may serve as a suitable model to test the effect of cardiac glycosides on EGFR signaling in medulloblastoma." (PMID 25052069, 2014). "Thus, we thought to investigate the relationship between Na,K-ATPase and EGFR signaling in medulloblastoma cells." (PMID 25052069, 2014). "Thus, aberrant EGFR/ErbB2 signaling has become an attractive therapeutic target for medulloblastoma." (PMID 25052069, 2014). "With its role in cell migration, relocation of FAK to stress fiber endpoints in EGF-treated cells supports the hypothesis that the EGFR signaling cascade might be involved in switching from random to directional movement, thus promoting tumor cell invasion in medulloblastoma cells." (PMID 25052069, 2014). "Moreover, Abouantoun and co-workers showed PDGFRB tyrosine kinase activity is critical for migration and invasion of medulloblastoma cells, possibly by trans-activating EGFR, and thus its depletion may represent an important therapeutic strategy for the treatment of this cancer." (PMID 28435517, 2017). "Blocking EFGR significantly inhibited the uPAR and MMP-9 induced EGFR and STAT3 activation in medulloblastoma cells compared to the cells treated with the isotype IgG." (PMID 22984561, 2012). "EGFR is not as well studied in medulloblastoma though there is data to support a synergism between EGFR and Hedgehog signaling in SHH tumors resulting in stabilization of the Gli1 protein." (PMID 29880060, 2018). "Furthermore, EphB1 can functionally interact with the epidermal growth factor receptor (EGFR), contributing to the metastatic behavior of medulloblastoma cells." (PMID 28194092, 2017). "Nevertheless, in medulloblastoma cells ouabain did not transactivate EGFR as has been reported in various other cell lines." (PMID 25052069, 2014). "Here, we show that consistent with previous studies, treatment of DAOY medulloblastoma cells with EGF activated the EGFR signaling cascade and resulted in increased phosphorylation of both the EGFR and the HER2/ErbB2 receptors as well as the downstream targets Erk1/2 and Akt." (PMID 25052069, 2014). "In addition, treating pre-established medulloblastoma with siRNAs against uPAR and MMP-9 both alone or in combination with radiation suppressed uPAR, MMP-9, EGFR, STAT3 expression and induced Bak activation leading to apoptosis." (PMID 22984561, 2012). "Two cases of medulloblastoma in this study expressed no EGFR." (PMID 33707521, 2021). "Our results show an appreciable decrease in the levels of phosphorylated EGFR and total EGFR following EphB1-specific siRNA treatment in DAOY cells, suggesting that the EphB1 receptor might be contributing to the metastatic behavior of medulloblastoma cells by functionally interacting with EGFR." (PMID 25879388, 2015). "Thus, we suggest that simultaneous targeting of Na,K-ATPase, EGFR, and possibly FAK signaling might as well confer therapeutic advantage in medulloblastoma." (PMID 25052069, 2014). "ErbB2 has been suggested to be involved in the migration of medulloblastoma cells 2,9,10, and in our studies DAOY cells treated with EGF were highly motile, suggesting that activation of the EGFR signaling cascade may play a role in medulloblastoma cell migration." (PMID 25052069, 2014). "In addition, in D283 cells, a cell line derived from medulloblastoma metastasis in the peritoneum, ouabain did not inhibit EGF-induced activation of Erk1/2 but reduced EGF-induced Akt activation and almost completely abolished EGF-induced EGFR phosphorylation." (PMID 25052069, 2014).
salivary gland cancer (36 papers, 2008 to 2025). A primary or metastatic malignant neoplasm that affects the major or minor salivary glands. "Recently, we identified two EGFR mutations in a cohort of 25 salivary gland carcinomas (SGCs) by screening the tumour samples for the both most common hotspot mutations in exons 19 and 21 by allele-specific PCR." (PMID 19174819, 2009). "By screening salivary gland carcinoma, two drug-sensitizing EGFR exon 19 delE746-A750 mutations were identified in an adenocystic and in a mucoepidermoid carcinoma of the parotid gland." (PMID 18542074, 2008). "EGFR kinase domain mutations are rare in salivary gland carcinomas." (PMID 25663934, 2015). "Approximately 40–70% of salivary gland cancers overexpress EGFR, and EGFR overexpression in recurrent or metastatic SGC was detected in 77.8% of cases." (PMID 38542206, 2024). "This study clearly demonstrated that NIR-PIT using the EGFR Affibody–IR700Dye conjugate represents a new treatment strategy for EGFR-positive salivary gland cancer that is less invasive and improves the quality of life." (PMID 38542206, 2024). "In this study, we investigated the effectiveness of NIR-PIT using a small protein mimetic, Affibody, instead of a monoclonal antibody for the treatment of EGFR-positive salivary gland cancer (SGC)." (PMID 38542206, 2024). "In this study, we investigated NIR-PIT using a small protein mimetic (6–7 kDa, Affibody) which has more rapid clearance and better tissue penetration than mAbs for epidermal growth factor receptor (EGFR)-positive salivary gland cancer (SGC)." (PMID 38542206, 2024). "This is the first ever report of NIR-PIT using the EGFR Affibody–IR700Dye conjugate for salivary gland cancer." (PMID 38542206, 2024). "Although further studies are required to examine the full therapeutic potential of this approach, NIR-PIT using the EGFR Affibody–IR700Dye conjugate is expected to become one of the most effective treatments for salivary gland cancer." (PMID 38542206, 2024). "Investigation of HER gene family member expression in salivary gland cancer showed that Mu and Wa subtypes had higher EGFR expression among the salivary gland cancer subtypes." (PMID 36137139, 2022). "Here, we investigated the association with PCP4/PEP19, EGFR, and HER2 in MEC, which is the most common malignant salivary gland tumor." (PMID 35008217, 2021). "Overexpression of EGFR was often observed in salivary gland cancers and provides a solid and sound rationale for the administration of cetuximab." (PMID 33296026, 2021). "On a larger cohort of salivary gland tumours, 134 of 663 salivary gland carcinomas were found with 3+ EGFR reaction and 80 of 189 salivary gland adenomas with 3+ EGFR reaction." (PMID 28377929, 2017). "EGFR overexpression is seen in salivary gland carcinomas and hence single agent cetuximab and gefitinib were studied in two negative phase 2 trials." (PMID 31093341, 2016). "To identify the genetic mutation that contributed to the pathogenesis of SDC, one of the most aggressive subtypes of salivary gland cancers, we investigated 18 SDC biospecimens to search for either somatic KRas or EGFR mutation." (PMID 26289340, 2015). "In agreement with both EGFR and ErbB2 overexpression, cetuximab and trastuzumab, which target EGFR and ErbB2, respectively, represent important tools for treatment of salivary gland carcinomas." (PMID 24886178, 2014). "The overexpression of EGFR is reportedly related to a poor prognosis in salivary gland cancer, which is different from our results." (PMID 23231994, 2012). "It has recently been shown that loss of PTEN is associated with elevated EGFR and HER2 expression and worse prognosis in salivary gland cancer, further demonstrating the importance of these two genes in other cancer types." (PMID 23319880, 2012).